MEG3 (maternally expressed 3)
Diseases named in the same sentence as MEG3 in open-access papers (continued):
Sharing a sentence is not in itself a finding about the gene and the disease.
lung carcinoma (continued). "In NSCLC tissues, MEG3 is downregulated; and the expression of MEG3 is lower in lung cancer cell lines A549 and HCC823." (PMID 34976181, 2022). "Autophagy exists in tumor cells, and downregulation of MEG3 can partially inhibit autophagy in lung cancer cells and can also regulate ATG3 activity to inhibit autophagy in epithelial ovarian cancer cells." (PMID 36523500, 2022). "At last, we treated lung carcinoma cells with inhibition of LncRNA MEG3, inhibition of miR-543, and inhibitor of the IDO signaling pathway NLG919, respectively, and detected the autophagy protein expression of each group." (PMID 34399782, 2021). "LncRNA MEG3 in the lung tissue of rats using IDO inhibitor was elevated compared with that of lung carcinoma model rats (P < 0.05)." (PMID 34399782, 2021). "For instance, elevated HOTAIR and reduced MEG3 have been shown to drive cisplatin resistance in lung cancer cells." (PMID 33803619, 2021). "The 54 enrolled lung cancer patients were divided into different groups according to the genotypes of the rs884225 SNP, the genotypes of the rs17337023 and their haplotypes of MEG3." (PMID 33635564, 2021). "It was suggested that LncRNA MEG3 can affect lung carcinoma cells and autophagy by regulating the miR-543/IDO signaling pathway." (PMID 34399782, 2021). "MEG3 is believed to be a tumor suppressor lncRNA because its expression is decreased in various human tumors, including lung cancer tissues." (PMID 32117734, 2020). "In lung carcinoma, downregulation of MEG3 enhances cisplatin resistance through the WNT/β‐catenin pathway activation." (PMID 32277605, 2020). "MEG3 (Maternally Expressed 3)-imprinted long non-coding RNA gene knockdown in lung cancer leads to enhanced antiproliferative and proangiogenic features of those cancer cells by affecting the SOX7 transcript." (PMID 33152990, 2020). "The MEG3 was also able to reverse cisplatin‐tolerance of lung adenocarcinoma cells by inducing cell apoptosis, and silencing of MEG3, conversely, improved cisplatin‐resistance of non‐small cell lung cancer cells via activation of WNT/β‐catenin signaling." (PMID 32618397, 2020). "An extensive literature indicated that MEG3 plays important roles in lung cancer, such as proliferation, apoptosis and epithelial–mesenchymal transition (EMT)." (PMID 29899163, 2018). "It has been indicated that silencing of MEG3 promotes cisplatin resistance of lung cancer via Wnt/β-catenin signaling pathway." (PMID 29899163, 2018). "Among the downregulated lncRNAs, MEG3 inhibits lung cancer tumor progression through MYC downregulation." (PMID 29490660, 2018). "In conclusion, Meg3 plays a suppressive role in EOC, which is consistent with the role of Meg3 in gastric cancer, cervical cancer, lung cancer and hepatocellular carcinoma." (PMID 28423647, 2017). "Recent study showed that activation of Rb protein causes decreased expression of DNMT1, allowing for increased MEG3 expression and decreased cancer cell growth in lung cancer cell." (PMID 29287592, 2017). "MEG3 levels also were suppressed in A549 lung cancer cells compared with normal human bronchial epithelial (NHBE) cells, and, similar to the TKO cells, re-constitution of MEG3 led to a decrease in cell proliferation and elevated apoptosis." (PMID 27832204, 2016). "In this study, we show that treatment with palbociclib, a CDK4/6 inhibitor currently used in the treatment of metastatic breast cancer, increased the expression of MEG3 in the lung cancer cell lines A549 and SK-MES-1." (PMID 27832204, 2016). "Additionally, it has been observed that diminished levels of lncRNA MEG3 expression correlate with an unfavorable prognosis among individuals diagnosed with lung cancer." (PMID 37705098, 2023).
lung carcinoma (continued). "All these evidences suggest that abundant MEG3 expression is important to maintain normal lung function and physiology, whereas reduced MEG3 expression favors proliferation and promotes the pathogenesis of common lung diseases such as asthma and lung cancer." (PMID 36726728, 2023). "In addition to miR-21-5p/SOX7, the downregulation of MEG3 increases cisplatin resistance of lung cancer cells via activation of the WNT/beta-catenin signaling pathway." (PMID 36778005, 2023). "The restoration of MEG3 expression suppressed tumor growth and induced apoptosis in several human cancer cell lines, including lung cancer A549 cells, tongue squamous cell carcinoma cell lines SCC-15 and CAL27, and gastric cancer cell lines SGC7901, AGS, MGC803, MKN45, and BGC823." (PMID 36851033, 2023). "MEG3 has also been shown to act as a miRNA sponge in lung cancer." (PMID 36544907, 2022). "Furthermore, Terashima and colleagues demonstrated that MEG3 knockdown inhibits TGFβ-induced EMT in lung cancer cell lines." (PMID 36231143, 2022). "In summary, MEG3 plays an important role in the development, progression and drug sensitivity of lung cancer, and maybe a new prognostic marker and potential therapeutic target for this malignancy." (PMID 34976181, 2022). "Several studies have shown that the expression of MEG3 is repressed in CSCs or cancer tissues, indicating that MEG3 may have inhibitory effects on cancer stemness, at least in the liver, head and neck, and lung cancers." (PMID 34069546, 2021). "The expression of MEG3 is decreased in lung cancer stem cells (LCSCs)." (PMID 34069546, 2021). "Besides, MEG3 alters the proliferation and invasion of lung cancer cells and plays as a promising target in lung cancer." (PMID 34558385, 2021). "Real‐time PCR and Western blot were used to further explore the impacts of rs17337023, rs884225, rs325797437, rs344501106, rs81286029 and rs318656749 polymorphisms on the interaction among MEG3, miR‐214 and EGFR 3’UTR in lung cancer tissues collected from 54 lung cancer patients." (PMID 33635564, 2021). "However, cancer cells with MEG3 knockout have a decreased rate of cisplatin-induced apoptosis, and the result is that lung cancer cells enhance cisplatin resistance by activating the WNT/β-catenin signaling pathway." (PMID 34199840, 2021). "Furthermore, MEG3 is expressed in low amounts in chemotherapy-sensitive lung cancer tissues, and upregulation of MEG3 inhibits autophagy by increasing the sensitivity to vincristine chemotherapy." (PMID 33061817, 2020). "In lung cancer, MEG3 could enhance the chemosensitivity through regulation the WNT/beta catenin signaling pathway and miR-21-5p/SOX7 axis." (PMID 31488093, 2019). "Another study indicated that a rs116907618 polymorphism in MEG3 did not significantly affect platinum-based chemotherapy response in lung cancer patients." (PMID 29615542, 2018). "So, the lncRNA MEG3 has been proposed as a tumor suppressor gene, able to induce a cancer drug cisplatinum-based sensitivity, as a DNA intercalating toxic mechanism in human lung cancer cells." (PMID 28904641, 2017). "In addition, Meg3 was identified as a suppressive gene in lung cancer, cervical cancer and hepatocellular carcinoma." (PMID 28423647, 2017). "Besides, MEG3 plays important role in the epigenetic regulation of epithelial-mesenchymal transition promotes in lung cancer." (PMID 28157702, 2017).
lung carcinoma (continued). "In lung cancers, significantly dysregulated lncRNAs have been reported, and many of them, e.g., PANDAR, DLX6-AS1, BCYRN1, HNF1A-AS1, ANRIL, MEG3, and others, are involved in lung cancer pathogenesis, cell proliferation, invasion and metastasis, and drug resistance." (PMID 27322209, 2016). "Therefore, the level of MEG3 could be used as a potential biomarker to gauge the response to cisplatin based chemotherapy in lung cancer." (PMID 29069869, 2017). "In addition to lung cancer, increasing MEG3 expression may also provide a therapeutic benefit in other tumor types." (PMID 27832204, 2016). "They then examined the correlation between MEG3 expression levels and EZH2 recruitment at specific genomic loci in A549 and LC-2/ad lung cancer cell lines." (PMID 40149464, 2025). "This is exemplified in various cancers: TUG1 in liver cancer; MEG3 and HOTAIRM1 in lung cancer; LINC00355 in bladder cancer; TUC338 in laryngeal squamous cell carcinoma; FTX in oral squamous cell carcinoma; and NNT-AS1 in pancreatic cancer." (PMID 39717771, 2024). "The ability of lung cancer cells to form spheres, express OCT4 and CD133, and develop a stem cell-like state were all boosted when MEG3 was suppressed." (PMID 39170516, 2024). "Upregulation of MEG3 promotes the protein level of solute carrier family 34 member 2 (SLC34A2) and curbs migration and invasion in lung cancer cells and lung CSCs by sponging miR-650." (PMID 39170516, 2024). "MEG3 levels were also suppressed in A549 lung cancer cells compared with normal human bronchial epithelial (NHBE) cells, and the re-expression of MEG3 led to a decrease in cell proliferation and an elevation in apoptosis." (PMID 36851033, 2023). "LncRNA MEG3 is expressed at low levels in lung cancer tissues and cells, with significantly lower expression in stage III + stage IV lung cancer patients compared to stage I + stage II." (PMID 37837401, 2023). "The activation of pRb by the treatment of lung cancer A549 and SK-MES-1 cells with palbociclib, a CDK4/6 inhibitor, increased the expression of MEG3, while the knockdown of pRb/p107 attenuated MEG3 gene expression." (PMID 36851033, 2023). "LncRNAs have become the key regulatory factors in development and progression of lung cancer, functioning as oncogenes (e.g., MALAT1, HOTAIR, H19 and ANRIL) or tumor suppressors (e.g., MEG3, GAS5, and TUG1)." (PMID 34976181, 2022). "The tumor suppressor gene lncRNA growth arrest‐specific 5 (GAS5) and MEG3 have been found to inhibit autophagy by suppressing the cleavage of LC3, thereby enhancing the chemosensitivity of lung cancer cells." (PMID 33931980, 2021). "Downregulation of tumor suppressor genes lncRNA maternally expressed 3 (MEG3) and AK126698 has been demonstrated to confer resistance to cisplatin in lung cancer cells by activating the Wnt/β‐catenin signaling pathway." (PMID 33931980, 2021). "First, the EV-RNA signatures, low EV-miR-21-5p and high miR-486-3p, MEG3 and XIST identified in this study require clinical validation in a larger patient cohort to confirm their prognostic relevance in ALK-translocated lung cancer." (PMID 30658414, 2019). "Maternally-expressed 3 (MEG3) forms RNA-DNA triplex structures with genes involved in the TGF-β pathway and ultimately modulates tissue invasion in breast and lung cancer cells." (PMID 28671581, 2017). "Little is known about overall lncRNAs function in drug resistance, but three lung cancer-related lncRNAs (lncRNA-AK126698, BC200, MEG3) have been studied in detail." (PMID 28968955, 2017). "We show that activation of pRb by treatment of lung carcinoma cells with palbociclib, a CDK4/6 inhibitor, increased the expression of MEG3 in a pRb-specific manner." (PMID 27832204, 2016).
lung carcinoma (continued). "To date, only a few lncRNAs (including MALAT1, HOTAIR, H19, MEG3, GAS5, ANRIL, and SOX2OT etc.)have been reported to be dysregulated and functionally characterized in lung cancer and most of the studies were based on microarray expression data." (PMID 26862852, 2016). "The authors proposed an intriguing hypothesis that MEG3’s interaction with JARID2 could regulate EZH2 recruitment, thereby facilitating the establishment of H3K27 trimethylation (H3K27me3) in lung cancer cells." (PMID 40149464, 2025). "As a result, overexpression of MEG3 markedly suppressed the viability and proliferation of both drug-resistant and non-resistant lung cancer cells." (PMID 37588204, 2024). "For instance, the data of other types of lung carcinoma were not obtained, so we were unable to find the specific role of LncRNA MEG3 in other types of lung carcinoma." (PMID 34399782, 2021). "The level of LncRNA MEG3 in the lung tissue of normally fed rats was elevated compared with that of the lung carcinoma model (P < 0.05), and that of rats using IDO inhibitor was also evidently elevated compared with that of the lung carcinoma model (P < 0.05)." (PMID 34399782, 2021). "In lung cancer, resistance to platinum-based chemotherapeutics can, in part, be explained through modulation of DNA repair pathways and cell cycle arrest by lncRNAs such as HOTAIR and MEG3." (PMID 33803619, 2021). "Besides, reducing MEG3 expression, engendered by dysfunctional pRb‐DNMT1 signaling, was documented to boost multiplication of lung cancer cells." (PMID 32618397, 2020). "Since DNMT1 has previously been shown to regulate MEG3 expression through methylation in human hepatocellular carcinoma and hepatic stellate cells, we next wanted to determine the effect of DNMT1 knockdown on MEG3 levels within these lung cancer cell models." (PMID 27832204, 2016). "In addition, MEG3 promotes NSCLC cell proliferation by aberrant downregulation, the levels of which are correlated with the course of lung cancer, tumor size, and prognostic status and strengthen the sensitivity of lung cancer cells to chemotherapeutic agents." (PMID 34235076, 2021). "Furthermore, MEG3 overexpression was able to re-sensitize A549/DDP cells to cisplatinum in vitro, and the downregulation of MEG3 enhanced sensitivity to cisplatinum in lung cancer cells through activation of the Wnt/β-catenin signaling pathway." (PMID 28904641, 2017).
gastric cancer (76 papers, 2015 to 2025). A primary or metastatic malignant neoplasm involving the stomach. "The FPRP scores of the relationship between MEG3 rs7158663 SNPs and gastric cancer susceptibility in different genetic models were all lower than the preset cut-off value of 0.5." (PMID 33119060, 2020). "We found 3 novel lncRNAs in the top 20 (FRGCA at 3, MALAT1 at 13 and MEG3 at 20) that were recently associated with gastric cancer." (PMID 27992375, 2017). "Recently, many studies had found that maternally expressed 3 (MEG3) inhibited non-small cell lung cancer (NSCLC) cell proliferation and that MEG3 was associated with a poor prognosis and promoted cell proliferation in gastric cancer." (PMID 27528026, 2016). "Interestingly, the MEG3 rs7158663 variant is found to be associated with increased susceptibility to lung, colorectal, and gastric cancers." (PMID 41141357, 2025). "However, there are certain defects in that we only consider two sites of one gene, and cannot comprehensively study the combined effects of multiple SNPS of the MEG3 gene on the risk of gastric cancer, which will be further explored in subsequent research." (PMID 33119060, 2020). "The present study was conducted to investigate the relationship between long noncoding RNA (lncRNA) materally expressed gene 3 (MEG3) single nucleotide polymorphisms (SNPs) and the risk of gastric cancer and to construct a genetic-environmental risk assessment model." (PMID 33119060, 2020). "Our research first found that MEG3 rs7158663 GA + AA carriers could significantly increase the risk of gastric cancer, and A was a risk allele of gastric cancer." (PMID 33119060, 2020). "For example, lncRNA MEG3 by acting as a ceRNA against miR-181 could modulate gastric cancer progression, which may serve as an underlying target for antineoplastic therapies." (PMID 32420340, 2020). "However, there were few studies on the relationship between MEG3 polymorphism and the risk of gastric cancer." (PMID 33119060, 2020). "Therefore, MEG3 rs7158663GA, AA genotype, GA+AA genotype, and A allele were associated with increased risk of gastric cancer." (PMID 33119060, 2020). "In summary, our study found that the MEG3 rs7158663 A allele could significantly increase the risk of gastric cancer and was a risk allele of gastric cancer." (PMID 33119060, 2020). "MEG3/miR-21 axis participates in the tumor progression and metastasis of gastric cancer through the regulation of EMT." (PMID 41476448, 2025). "Significantly, MEG3's expression in gastric cancer tissue was correlated with the size of the tumor." (PMID 38294554, 2024). "In a study of gastric cancer, MEG3 overexpression inhibits the expression of miR-21 and inhibits cell proliferation and metastasis." (PMID 36523500, 2022). "Here we aimed to investigate the expression of MEG3 and HOTAIR in gastric cancer tissues and evaluate their association with the H. pylori status." (PMID 35186192, 2022). "It has been reported MEG3 inhibited tumor metastasis by regulating the Wnt/beta-catenin pathway in oral squamous cell carcinoma, regulating the expression of miR-21 in gastric cancer (GC), and miR-183 expression in human pancreatic cancers." (PMID 34381023, 2021). "In contrast, the sequestration of miR-181-a enabled MEG3 to up-regulate Bcl-2 in the case of gastric cancer." (PMID 33422052, 2021).